TERT (telomerase reverse transcriptase)
Diseases named in the same sentence as TERT in open-access papers (continued):
Sharing a sentence is not in itself a finding about the gene and the disease.
glioma (continued). "Integrated analysis of molecular key hallmarks in glioma (IDH, TERT, MGMT methylation, and LOH 1p/19q) and EGFR amplification showed that EGFR amplification is a phenomenon that can be predominantly found in IDH wildtype and TERT mutated gliomas, as well in gliomas without LOH 1p/19q." (PMID 35453544, 2022). "However, few studies evaluate the feasibility of ADC in predicting TERT and MGMT status in WHO grade II-IV gliomas." (PMID 36471242, 2022). "It is known that TERT expression is not a sufficient surrogate marker for telomerase activity in cancers, which has not been clearly characterized in gliomas." (PMID 35953846, 2022). "Grade III gliomas express upregulation of TERT when compared to grade II, p = 0.009, without any significance to the peritumoral tissue." (PMID 34194624, 2021). "Sequencing analyses revealed that KNS1451 did not harbor glioma-related driver mutations, such as IDH1/2, BRAF, and H3F3A, except for the TERT promoter C250T mutation detected by Sanger sequencing." (PMID 33387197, 2021). "One region on chromosome 5 (982,252–2,132,442 bp), harboring the TERT and CLPTM1L genes, showed significant local genetic correlation across six pairs of cancers, including ER-negative breast, colorectal, glioma, lung, melanoma, pancreatic, and prostate cancer." (PMID 34355204, 2021). "Other potential targets, such as TERT promotor mutation, although is considered to be the most common molecular alterations in IDH wild-type GBM, have not become a major target for glioma therapy yet." (PMID 34715891, 2021). "In glioma, a number of oncogenic landmarks have been identified previously, such as somatic alternations on IDH, O-6-methylguanine-DNA methyltransferase (MGMT) promoter, TERT promoter, and chromosome 1p/19q co-del." (PMID 34540693, 2021). "The study reported that reactive gliosis samples did not contain C228T or C250T mutations in the TERT promoter region, while 78% of IDH wild type gliomas were found to have pTERT mutation." (PMID 33547950, 2021). "Collectively, the results presented in this section point to GSH, NAD(P)/H, aspartate, and AXP as potential 1H-MRS-detectable biomarkers of TERT status and to glutamate, α-KG, alanine, and AXP as potential biomarkers of ALT status in low-grade gliomas harboring IDHmut." (PMID 33397920, 2021). "Moreover, additional genetic events, such as ATRX, TERT, and BRAF, which also frequently occur in IDH-mutant glioma, should be considered in future investigations." (PMID 34440884, 2021). "To summarize, perfusion parameters of glioma maybe related to the degree of tumor malignancy and the status of IDH, MGMT and TERT." (PMID 34814870, 2021). "Furthermore, we performed integrated analysis of molecular key hallmarks in glioma (IDH, TERT, MGMT methylation) and PD-L1 expression." (PMID 33963441, 2021). "In IDHwt GBMs, maintenance of the telomeres is mainly achieved through mutations of the TERT promoter, while in IDH-mutated (non-codeleted) gliomas, ATRX alteration is frequently observed." (PMID 32642724, 2020). "In the present study, SEL1L overexpression associates significantly with TERT promoter mutation, EGFR gene amplification, LOH on 10q and (borderline) 9p chromosomes, all well‐known negative prognostic markers for gliomas." (PMID 31111685, 2020). "In contrast, primo-cell cultures from three BRAFV600E-positive glioma specimens not expressing TERT mRNA and not developing into stable cell models were TERT promoter-wild-type." (PMID 31391125, 2019). "Thus, we suppose that aberrant expression of NAF1 will impact the translation of key molecules in malignant progression of gliomas such as c-Myc, NRF2, and TERT, which have been demonstrated to regulated NAF1 transcription." (PMID 30936423, 2019). "Sequencing of the TERT promoter region is the only method to detect this alteration; in several studies of multiple cancer types, including gliomas, TERT immunohistochemistry does not correlate with promoter mutation status." (PMID 30967140, 2019).
glioma (continued). "Therefore, we established a panel of twelve glioma-derived cell lines with different BRAF and TERT promoter status, containing nine BRAFV600E-mutant and three BRAF wild-type cell models." (PMID 31391125, 2019). "Several clinical trials that target TERT and telomere function are ongoing for different types of diseases but currently not for glioma." (PMID 31842352, 2019). "Finally, the relationship between the TERT promoter mutations, the expression levels of TERT protein, and tumor entity was further verified by Western blotting, and the level of TERT mRNA was not parallel with its mutational status across all the glioma samples (data not shown)." (PMID 29693015, 2018). "Surprisingly, glioma cells in all the cases showed nuclear immunostaining for TERT to various degrees compared with the cells in nonneoplastic tissues although some intratumoral heterogeneity of the nuclear staining was observed." (PMID 29693015, 2018). "Moreover, the expression of some key factors in gliomas were detected by QPCR, such as IDH1, TERT, EGFR, PTEN, ATRX." (PMID 28199986, 2017). "The second subtype of lower-grade gliomas had IDH mutations but lacked 1p/19q co-deletion and TERT promoter mutations." (PMID 26758195, 2016). "RNA expression data to investigate the relation between TERT promoter methylation and TERT expression was not available for our pilot set of gliomas." (PMID 27780202, 2016). "For example, ectopic expression of TERT has been shown to potentiate CSC properties in breast cancer cells in vitro, whereas telomerase inhibition was shown to deplete CSC in pancreatic, prostate, lung, breast, and glioma cell lines." (PMID 27240403, 2016). "Cells treated with 50 μM TMZ or the equivalent volume of DMSO had nearly identical luciferase activity, suggesting that TERT transcription in glioma cells was not blocked by TMZ." (PMID 24937153, 2014). "Distinguishing different astrocytoma subtypes based on TERT promoter mutation status could provide a molecular basis for pursuing more intensive treatments, although the present results indicated that high-grade glioma patients harboring the mutations did not respond well to chemo- and radiotherapy." (PMID 24937153, 2014). "Colony formation was apparent with the C6 glioma positive-control cells, but there was no colony formation in untransfected or TERT-transfected BMSCs." (PMID 24887495, 2014). "Variants of the TERT and RTEL genes are predominantly associated with glioblastoma, whereas variants of the CDKN2A and EGFR genes are associated with overall glioma risk, not with a specific subtype." (PMID 23236348, 2012). "Interestingly, 3 out of 13 gliomas did not present mutations in IDH, TERT, or EGFR, and were thus classified as “Diffuse gliomas IDH-wild type NEC (Not Elsewhere Classified)”." (PMID 41567539, 2025). "Interestingly, none of the cases had mutations in either TERT or ATRX, indicating they are mutually exclusive in MM, similar to those observed in gliomas." (PMID 37649078, 2023). "Therefore, further restricting the FGFR1 sequencing analysis to non-diffusely growing gliomas/MNGT tumors would yield 15% FGFR1 N546/K656 mutant cases after exclusion of cases with BRAF fusion, IDH1/2, NF1 or TERT mutation." (PMID 35018490, 2022). "Of all analyzed TERT wildtype gliomas, none show an EGFR amplification." (PMID 35453544, 2022). "Consistent with this hypothesis, a study performed in gliomas showed that decitabine-mediated proliferation arrest can be blocked by silencing of DNMT1, and overexpression of TERT correlated with an increase in DNMT1 levels, which improved decitabine sensitivity in the meanwhile." (PMID 35838271, 2022). "We show through the direct measurement of telomerase activity and ALT in a large set of glioma samples that the TMM in glioma cannot be defined solely by the combination of telomerase activity and ALT, regardless of TERT expression, TERT promoter mutation, and ATRX loss." (PMID 35953846, 2022).
glioma (continued). "In addition to monitoring the expression of TERT and DNMT1 to predict sensitivity to decitabine in gliomas, the miRNA-DNMT1 axis plays an essential role in drug resistance and could be applied to overcome azacitidine resistance." (PMID 35838271, 2022). "Consequently, in this study we investigated the mRNA expression level of TERT and all GABPA/B isoforms and their correlation and interplay in the grade II, grade III gliomas as well as in the primary and secondary glioblastomas to understand their role in the gliomagenesis." (PMID 34194624, 2021). "Our results revealed the expression of PON1 was crucially positive associated with SSTR3 in glioma, while there were a crucial negative association between the expression of PON1 and TERT, and the expression of LEP was negatively associated with PON1 and SSTR3." (PMID 34114970, 2021). "TERT promoter mutation is a negative prognostic factor, but mainly in IDH-wildtype gliomas." (PMID 34638714, 2021). "The biological mechanism of interaction between TERT promoter mutation and MGMT methylation that may influence sensitivity to TMZ treatment of gliomas has not yet clearly defined." (PMID 32957941, 2020). "Moreover, given that glioma sub-types are stratified according to the MGMT promoter methylation status, wherein telomerase reverse transcriptase (TERT) status showed distinct tumor characteristics and OS outcomes, we investigated the prognostic value of risk score in these populations." (PMID 31921684, 2019). "However, we surprisingly found that knockdown or ectopic expression of NAF1 in glioma cells also impacted mRNA levels of c-Myc, NRF2, and TERT, suggesting that there may exist unknown mechanisms of NAF1 modulating gene transcription." (PMID 30936423, 2019). "The absence of MGMT promoter methylation is an additional negative prognostic factor in TERT mutated GBM, and assessment of MGMT promoter methylation status assists in better defining prognosis for patients with gliomas, due to the role of this feature as a predictive marker of therapeutic efficacy." (PMID 28915660, 2017). "Interestingly, we found that IDH wt/TERT wt WHO grade II and III diffuse gliomas did not respond to genotoxic therapies as well as other gliomas with either IDH mutations or TERT promoter mutations." (PMID 26314843, 2015). "Moreover, due to the heterogeneity of gliomas themselves, there is no baseline for making comparisons of TERT expression." (PMID 24937153, 2014). "This study supports genotyping of TERT promoter and IDH1/2 in gliomas as a rapid economical test requiring little tumoral DNA that could help inform clinicians as to the predicted OS of these tumors that may differ from their predicted outcomes based on conventional histology alone." (PMID 24722048, 2014). "However, further research is needed to determine whether the loss of ATRX is associated with epigenetic landscape reprogramming, as well as increased levels of telomerase reverse transcriptase (TERT) and alternative lengthening of telomeres (ALT) expression, in glioma subtypes." (PMID 40210723, 2025). "Understanding the biological role of MGMT promotor status and its clinical impact in the presence of TERT promotor mutations and absence of IDH mutations in gliomas formerly assigned to WHO grade II and III may be of great importance for future therapeutic management of such patients." (PMID 34902093, 2022). "Likewise, no prognostic significance was found for PLR and AGR in the IDH and TERT mutation group, MLR and AGR in the IDH mutation only group, MLR and AGR in the TERT mutation only group, and PLR, MLR, and AGR in the triple-negative group of lower-grade gliomas." (PMID 31444316, 2019).
glioma (continued). "Considering the relationship between burden of glioma risk alleles and survival in each molecular subgroup a consistent association with increased survival was shown in Triple-positive, Triple-negative and TERT-only molecular groups but not in IDH-only and TERT-IDH groups." (PMID 29460007, 2018). "Additionally, it has been proposed that associations may exist between risk SNPs at 5p15.33, 9p21.3 and 20q13.33 and IDH wild-type glioma, as well as 17p13.1 and TERT promoter, IDH mutated glioma without 1p/19q co-deletion." (PMID 29460007, 2018). "However, gliomas typically do not express histiocytic markers and exhibit other molecular characteristics, including IDH mutations, ATRX alterations, 1p/19q co-deletions, EGFR amplification, TERT promoter mutations, H3 mutations, MYB/MYBL1 gene structural mutations, and FGFR1 mutations, etc." (PMID 40231251, 2025). "In grade III gliomas, GABPB1 negative correlates with TERT significantly (r = −0.65, 95% CI = −0.85–0.27; p = 0.003)." (PMID 34194624, 2021). "In this study, we found that the mutant genes in the metastatic brain tumors included ALK, MDM2, ATM, BRCA1, FGFR1, and KRAS, and there were no glioma-related mutant genes (MGMT, IDH1, IDH2, 1p/19q, BRAF, and TERT)." (PMID 32973641, 2020). "Our clinicopathological study showed a higher prevalence of triple-negative gliomas (IDH wildtype, 1p/19q no-codeletion and TERT promoter wildtype WHO II&III gliomas) in Chinese glioma patients." (PMID 32047544, 2020). "However, multivariate analyses have shown that TERT does not represent an independent prognostic factor when IDH-Mutant and Wildtype grade 4 gliomas are analyzed separately." (PMID 39273661, 2024). "Previous studies indicate that TERT inhibition could lead to the development of resistance via the ALT pathway in other cancers, although studies in gliomas are lacking." (PMID 33397920, 2021).
glioblastoma (421 papers, 2012 to 2026). The most malignant astrocytic tumor (WHO grade IV). "Of all 39 TERT mutated glioblastomas, 17 tumors (44%) showed CDKN2A/B loss and 22 tumors (56%) showed retained CDKN2A/B." (PMID 41438586, 2026). "Of all 42 glioblastomas with known TERT mutation status, TERT mutation were found in 39 cases (93%) while TERT wildtype status was found in only three cases (7%)." (PMID 41438586, 2026). "Of the three TERT wildtype glioblastomas, one case (33%) showed CDKN2A/B loss while two cases (66%) showed retained CDKN2A/B." (PMID 41438586, 2026). "Telomerase reverse transcriptase (TERT) promoter mutations are observed in most glioblastoma (GBM) tumors, leading to TERT expression, which is crucial for tumor growth." (PMID 40463649, 2025). "TERT promoter mutations (TERTp) occurs in approximately 80% of IDH-wildtype glioblastomas and enable tumor cells to evade replicative senescence, contributing to the malignant phenotype." (PMID 41346390, 2025). "IDH-wildtype glioblastomas typically occur in older adults, exhibit aggressive biological behavior, and frequently harbor genetic alterations, such as TERT promoter (TERTp) mutations and epidermal growth factor receptor (EGFR) amplification." (PMID 41473634, 2025). "The 624-mel cell line contained a mutated BRAF gene (Val600Glu), while both glioblastoma cell lines are characterized by a TERT promotor mutation and a CDKN2C deletion." (PMID 40955425, 2025). "Glioblastoma patients with TERT mutations had a shorter survival period and an overall poorer prognosis than those without the mutations." (PMID 40564017, 2025). "TERT promoter mutations are one of the most common mutations in glioblastoma, identified in 70–80% of cases and are associated with poor prognosis." (PMID 41212363, 2025). "Lastly, we purified TNC+ EVs from plasma of 21 glioblastoma patients by magnetic sortingand detected the oncogenic mutation TERT*C228T bydroplet digital PCR." (PMID 40056466, 2025). "In primary glioblastoma and oligodendroglioma, the frequency of TERT promoter mutations is approximately 80%, whereas in astrocytoma, the incidence of such mutations is only about 10%." (PMID 39871386, 2025). "These mutations induce expression of the TERT oncogene by creating a GABPA transcription factor binding site in glioblastoma and melanoma." (PMID 40359938, 2025). "The C228T mutation in TERT is present in 76.47% of primary glioblastoma patients and is associated with poor prognosis." (PMID 39871386, 2025). "TERT promoter mutations are found in about 80% of glioblastoma patients and are typically diagnosed by DNA sequencing." (PMID 39796751, 2025). "The mean ADC ratios of patients with glioblastoma exhibiting the TERT promoter C228T mutation (mean 1.25 ± 0.25) and those with wild type (mean 1.63 ± 0.27) differed significantly." (PMID 40866807, 2025). "The sorted TNC+ and TNC– EV fractions were evaluated by droplet digital PCR(ddPCR), in order to compare allele frequencies of TERT*C228T, the most common mutation in glioblastoma patients." (PMID 40056466, 2025). "In a clinical setting, significant findings reveal that TERT promoter (TERTp) mutations are prevalent in approximately 80% of glioblastomas, facilitating telomere maintenance and cancer advancement." (PMID 41154393, 2025).